FAT2 (FAT atypical cadherin 2)
Description:
Involved in the regulation of cell migration. May be involved in mediating the organization of the parallel fibers of granule cells during cerebellar development (By similarity).
Synonyms: hFat2; CDHF8; MEGF1; CDHR9; SCA45
Tractability: Antibody: UniProt places it where antibodies can reach, with high confidence; UniProt predicts a signal peptide or a membrane-spanning region; its Gene Ontology location is reachable by antibodies, with medium confidence. PROTAC: ubiquitination databases record sites on it.
Gene: Protein-coding gene on chromosome 5 (151,504,092 to 151,591,331, reverse strand). Ensembl gene ENSG00000086570.
Subcellular location: Cell membrane; Cell junction; Golgi apparatus, trans-Golgi network
Subcellular location (Human Protein Atlas): Vesicles
Gene Ontology:
Molecular function: calcium ion binding
Biological process: cell-substrate adhesion; epithelial cell migration; cell-cell adhesion mediated by cadherin; homophilic cell-cell adhesion; cell adhesion; cell-cell adhesion
Cellular component: adherens junction; anchoring junction; extracellular exosome; plasma membrane; cell-cell junction; Golgi apparatus; membrane
Genetic constraint (gnomAD): Loss-of-function variants: 145 observed, 300.4 expected, observed/expected ratio (o/e) 0.48, 90% interval 0.42 to 0.55. The upper end of that interval is the gene's LOEUF score, 0.55, which puts it in group 2 of 6, group 1 being the genes least tolerant of losing a copy. Missense variants: 4,867 observed, 5,709.2 expected, observed/expected ratio (o/e) 0.85, 90% interval 0.83 to 0.87. Synonymous variants: 2,025 observed, 2,259.9 expected, observed/expected ratio (o/e) 0.9, 90% interval 0.86 to 0.93.
Homologues: Orthologues: chimpanzee FAT2 (99% identical), macaque FAT2 (97% identical), rabbit FAT2 (87% identical), pig FAT2 (85% identical), guinea pig FAT2 (83% identical), mouse Fat2 (82% identical), rat Fat2 (82% identical), dog FAT2 (81% identical), tropical clawed frog FAT2 (51% identical), zebrafish fat2 (46% identical), Caenorhabditis elegans hmr-1 (15% identical), Drosophila melanogaster stan (11% identical), and 2 more. Paralogues in human: FAT1 (44% identical), FAT3 (42% identical), FAT4 (26% identical), CELSR1 (12% identical), CELSR3 (12% identical), CELSR2 (12% identical).
Diseases named in the same sentence as FAT2 in open-access papers:
FAT2 is named in the same sentence as 52 diseases in open-access papers, as found by Europe PMC text mining. Sharing a sentence is not in itself a finding about the gene and the disease. The quoted sentences say what the papers report.
breast carcinoma (6 papers, 2016 to 2026). "Upregulation of JAG1 and FAT2 has furthermore been linked to poor prognosis in breast cancer, and a Jagged-1/Notch2/PDGFR stroma–epithelial mechanism has been described in a poor prognosis fibroblast subset." (PMID 38172915, 2024). "p63 is known to induce the expression of human FAT2, as well as the mesenchymal gene Slug, to promote tumor invasion in breast cancer, whereas COTL1 increases the migratory ability of both breast and non-small cell lung cancer cells." (PMID 36672394, 2023). "Gene enrichment analysis in terms of Jensen DISEASES revealed that genes with germline variants (PLXNA2, FAT2, and SYNE1) enriched in the Maltese breed are also enriched in several cancers, such as endometrial cancer (p < 0.01), pancreatic cancer (p < 0.05), and breast cancer (p < 0.05)." (PMID 31842489, 2019). "Recombinant FAT2 protein was generated, and its effects on migration, invasion, and epithelial-mesenchymal transition (EMT) were assessed in HER2-positive breast cancer cell lines (BT-474 and MDA-MB-453)." (PMID 42052461, 2026). "To prioritize non-mesenchymal genes for further investigation, we determined how the expression of FAT2, SNCA, CPNE8, NEK1 and CA12 correlated with ΔNp63α mRNA levels in breast cancer patient tumors analyzed by TCGA." (PMID 27081041, 2016).
Ataxia (5 papers, 2019 to 2025). Ataxia refers to impaired coordination of voluntary muscle movement. "Variants of FAT2 have been identified in females with autism and in spinocerebellar ataxias." (PMID 40779003, 2025). "Therefore, studying autophagic flux and neurodegeneration in Fat1 deficient or Fat2 deficient mice will be of high future interest in order to investigate the cellular mechanisms that underlie the role of those two Fat homologues in ataxia." (PMID 31695130, 2019).
lung carcinoma (5 papers, 2016 to 2022). "However, we also confirmed protein expression in patient specimens for two novel lung cancer targets, i.e. FAT2 and KiSS-1R." (PMID 29371917, 2017). "Five of these markers, CXorf61, DSG3, FAT2, GPR87, and LYPD3, were selected based primarily on their high and broad expression among the lung cancer samples relative to normal lung." (PMID 29371917, 2017). "Examples of these such as FAT2 and LRRC7 have known roles in various cancers including lung cancer." (PMID 35999530, 2022). "As for the genetic landscape in detail, several incidences of mutated genes that were adverse to prognosis were observed to be lower in the young lung cancer group (LRP1B, SMARCA4, STK11, FAT2, RBM10, FANCM), which may explain the better prognosis of the young lung cancer group to some extent." (PMID 35096611, 2021).
gastric cancer (4 papers, 2021 to 2025). A primary or metastatic malignant neoplasm involving the stomach. "The mutation and expression of FAT2 could affect the survival and prognosis of gastric cancer patients, for which FAT2 mutation was associated with better patient prognosis." (PMID 36812126, 2023). "Our results were consistent with findings in other tumor studies investigating gastric cancer, LUAD, and NSCLC, for which patients with FAT2 mutations had a better prognosis." (PMID 36812126, 2023). "FAT2 gene is widely expressed in human normal tissues such as brain tissue and tumor tissues such as esophageal carcinoma, gastric cancer, and ovarian cancer." (PMID 36812126, 2023). "Of note, Krt18 is correlated with the malignant status and acts as an oncogene in colorectal cancer as for FAT2, an independent prognostic factor for the poor prognosis of gastric carcinoma." (PMID 35572581, 2022). "However, studies on FAT2 in gastric cancer are relatively scarce." (PMID 34308747, 2021).
autism (3 papers, 2017 to 2025). Persistent deficits in social interaction and communication and interaction as well as a markedly restricted repertoire of activity and interest as well as repetitive patterns of behavior. "Fat2 close homologs, namely Fat1-3, exist in vertebrates and have been implicated in cancer and autism." (PMID 29176774, 2017). "Protocadherin FAT2 protein was downregulated in adult subjects with autism." (PMID 40779003, 2025).
pancreatic cancer (3 papers, 2019 to 2023). "Given our findings that BRDT colocalized with ΔNp63 on several genes such as FAT2 and PTHLH, which we previously demonstrated as being associated with ΔNp63-dependent SEs in pancreatic cancer, we investigated whether BRDT, like BRD4, may be a defining feature of SEs in a subset of ESCC." (PMID 33658703, 2021). "In a previous study, FAT2 was found to share the signaling pathway like Ena/VASP, which affects progression of gastric and pancreatic carcinoma." (PMID 36812126, 2023).
embryonal tumors (2 papers, 2023 to 2024). "For example, FAT2 was significantly decreased (estimate = −1.80) in embryonal tumors relative to non-tumor tissue in the adjusted model but significantly increased (estimate = 0.42) in embryonal tumors in the unadjusted model." (PMID 36865335, 2023).
lung adenocarcinoma (2 papers, 2016 to 2024). A carcinoma that arises from the lung and is characterized by the presence of malignant glandular epithelial cells. "FAT2 showed the strongest correlation with ΔNp63α, so we further investigated the relationship between FAT2 and ΔNp63α expression in lung squamous cell carcinoma, lung adenocarcinoma, bladder cancer, prostate cancer and pancreatic adenocarcinoma tumors analyzed by TCGA." (PMID 27081041, 2016). "Tumor cells with high levels of FAT2 expression also show a significant upregulation of the chemokine genes, including CCL2, CCL3, CCL4, CCL19, CXCL10, and CXCL11, in lung adenocarcinoma tissues." (PMID 38303018, 2024).
bladder cancer (1 paper, 2016). "Notably, ΔNp63α expression also correlated with FAT2 expression across a wide-range of tumors, with Slug also showing a strong correlation in lung SCC, prostate and bladder cancer." (PMID 27081041, 2016).
clear cell renal cell carcinoma (1 paper, 2017). "FAT2 was frequently mutated in clear cell renal cell carcinoma." (PMID 28673244, 2017).
head and neck squamous cell carcinoma (1 paper, 2012). A squamous cell carcinoma that arises from any of the following anatomic sites: lip and oral cavity, nasal cavity, paranasal sinuses, pharynx, larynx, and salivary glands. "Non-synonymous mutations of human FAT2 and FAT4 genes are detected in 1 and 2 out of 32 cases of head and neck squamous cell carcinoma (HNSCC), respectively." (PMID 23076869, 2012).
lung squamous cell carcinoma (1 paper, 2016). "Notably, lung squamous cell carcinoma migration also required ΔNp63α dependent FAT2 and Slug expression, demonstrating that ΔNp63α promotes migration in multiple tumor types by inducing mesenchymal and non-mesenchymal genes." (PMID 27081041, 2016).
meningioma (1 paper, 2024). A generally slow growing tumor attached to the dura mater. "Although to a rarer extent, additional Hippo Pathway inhibitors, such as FAT2 in spinal meningiomas, can also be mutated in meningioma, further highlighting the role of deregulated Hippo-YAP signaling in meningioma." (PMID 38571886, 2024).
ocular coloboma (1 paper, 2022). "Variants in other members of this family, FAT1 and FAT2, were found to be associated with recessive syndromic ocular coloboma and dominant spinocerebellar ataxia-45." (PMID 35885948, 2022).
squamous carcinoma (1 paper, 2021). "FAT2 knockdown inhibits the migration of human squamous carcinoma cells and induction of FAT2 by ΔNp63α promotes tumor invasion, indicating that alterations in FAT2 expression play a role in the development of tumors." (PMID 34308747, 2021).
cancer (22 papers, 2012 to 2025). A tumor composed of atypical neoplastic, often pleomorphic cells that invade other tissues. "While some cancer-associated genes were downregulated, such as potassium channel 6.1 (Kir6.1), the atypical cadherin, FAT2, and keratin 18 (Krt18)." (PMID 35572581, 2022). "Another evidence of a possible direct effect of H89 on cancer cells is its ability to reduce the transcripts of certain tumor markers, such as keratin 18 (Krt18) and atypical cadherin (FAT2)." (PMID 35572581, 2022). "Mutations in FAT atypical cadherin 2 (FAT2), a gene associating with several cancers, and those in TET3, a member of the TET gene family, were identified in 3 and 2 cases, respectively." (PMID 28157189, 2017). "In addition to human orthologs previously identified as playing key roles in OSCC, p63 signaling, and other cancers, namely, FAT2, K14, and PERP, we identified several novel regulators, including Cotl1, Bcam, Adipor2, and Wnt7b." (PMID 36672394, 2023). "The score system identified FAT2 (FAT atypical cadherin 2) as a probable driver gene in two samples, because it is a gene ranked B in CCGD, also frequently mutated in cancers and variants were considered pathogenic in three out of four prediction models of cancer causality investigated." (PMID 29854292, 2018). "FAT2 may be involved in cancer aggressiveness, which remains inconclusive." (PMID 39208202, 2024). "There were also studies showing that, as an atypical cadherin, FAT2 could exert biological functions through the Hippo pathway, which is closely related to the maintenance of tissue homeostasis and to multiple processes including cancers." (PMID 36812126, 2023). "Among them RB1 or ATM have a relatively clear rational and were reported be associated with poor prognosis in other types of cancer, but genes such as FAT2 or SMARCA4 may represent novel resistance genes." (PMID 27285986, 2016). "Other members of FAT gene family, i.e., FAT1, FAT2 and FAT3, have been extensively characterized in various cancers recently." (PMID 26672766, 2016). "However, the associations of other genes used in our model with ICI efficacy have not been reported, although some of them have been found to play critical roles in cancer, such as COL5A2, FAT2, ITPR3, PCDH20, and UTRN." (PMID 35557959, 2022). "In addition, the non-canonical Wnt/PCP pathway (FAT2, CELSR1, WNT5A), known to suppress early-staged cancers by regulating cell adhesion or migration, was downregulated in group 3." (PMID 30699951, 2019).
tumor (20 papers, 2010 to 2026). "Tumor mutation burden (TMB) values of the FAT2 mutant and non‐mutant groups were computed by Wilcoxon rank sum test." (PMID 36812126, 2023). "In this study, we found that patients with FAT2 mutations showed better prognosis, suggesting that these mutations play a role in tumor suppression in GC." (PMID 34308747, 2021). "FAT2 encodes a tumor suppressor essential for controlling cell proliferation during Drosophila development." (PMID 28673244, 2017). "Moreover, we investigated the expression differences of various immune cells between FAT2 mutation and wild‐type tumor tissues." (PMID 36812126, 2023). "However, the effect of FAT2 mutations on survival and the mechanism by which FAT2 mutations affect tumor progression in GC remain unclear and require elucidation." (PMID 34308747, 2021). "The most affected oncogenic signaling pathways in our NB tumor samples were RTK-RAS, NOTCH, and Hippo, which are linked to primary mutations in ALK, NCOR2, and FAT2, respectively." (PMID 39338204, 2024). "One tumor was positive for HPV45 and had mutations in FAT1 and FAT2; the other was positive for HPV31 and had mutations at NOTCH1, MAPK1, and HIST1H2AK." (PMID 38058352, 2023). "We stratified tumor cases containing FAT1 and FAT2 alterations, including mutations, copy loss alterations or loss of expression (n = 188) and compared them to those exhibiting unaltered FAT1 and FAT2 (n = 76)." (PMID 29985391, 2018). "Conversely, cluster 4 was mainly characterised by the presence of genes involved in signal transduction and cell structure, including a number of tumour suppressor genes (FAT-2, DCC, RASSF-4 and BRAF) that play a role in the control of cell proliferation." (PMID 20700504, 2010). "In lung adenocarcinoma (LUAD), FAT2 mutations could predict prognosis independently, which was correlated with higher tumor mutation burden (TMB) and tumor‐infiltrating immune cells (TICs)." (PMID 36812126, 2023). "The ability of FAT2 and Slug to promote migration suggested that their expression may influence clinically relevant features of tumor progression." (PMID 27081041, 2016). "Indeed, there was a strong correlation between ΔNp63α and FAT2 expression across the different tumor types." (PMID 27081041, 2016). "Thus, our results indicate that FAT2 and Slug are part of a conserved ΔNp63α dependent gene expression program that is essential for migration in distinct tumor types." (PMID 27081041, 2016). "Finally, in the CD6 model, we noted that the primary tumor did not harbor the FAT2 variant (c.6838del) observed in the corresponding xenograft." (PMID 35326637, 2022). "FAT atypical cadherin 2 (FAT2) is a homolog of the Drosophila fat gene, which is involved in Hippo signaling cascades and tumor suppression." (PMID 34308747, 2021). "FAT1, FAT2, FAT3 and FAT4 are human homologs of Drosophila Fat, which is involved in tumor suppression and planar cell polarity (PCP)." (PMID 23076869, 2012).
immune system diseases (1 paper, 2018). "DEGs that enriched to “immune system diseases” played critical roles in cell-matrix communication (THY1, LVRN, LUM, TIMP3, SPOCK1, LGALS3BP, FAT2, and SERPINE2) as well as inflammation (IL1R2, CD22, PTGES, TNFSF10, IL2RB, C3, SERPING1, and IL-17RE)." (PMID 30131724, 2018).
infection (1 paper, 2023). The state of being infected such as from the introduction of a foreign agent such as serum, vaccine, antigenic substance or organism. "In addition, the infection caused by A. hydrophila resulted in significant changes in the transcription of epithelial proliferation and migration-related genes, including tp63, fat2, and Itgb4, when compared to control fish." (PMID 37908355, 2023).
lung (1 paper, 2016). "Our study showed that ΔNp63α regulates migration through inducing Slug and FAT2 expression in a lung SCC population." (PMID 27081041, 2016).
FAT2 also shares sentences with these, for which no sentence is quoted: colorectal cancer (3 papers); endometrial cancer (2); acinar cell carcinoma (1); adenocarcinoma (1); Alagille syndrome (1); Areflexia (1); bacterial infection (1); cerebellar ataxia (1); cervical cancer (1); eccrine porocarcinoma (1); esophageal cancer (1); esophageal squamous cell carcinoma (1); glioblastoma (1); glioma (1); holoprosencephaly (1); liver cancer (1); myopathy (1); neurological disorders (1); non-small cell lung carcinoma (1); Obesity (1); Onset (1); oral cancer (1); ovarian carcinoma (1); pancreatic adenocarcinoma (1); pancreatic ductal adenocarcinoma (1); Parkinsonism (1); paroxysmal non-kinesigenic dyskinesia (1); prostate carcinoma (1); schizophrenia (1); Tay-Sachs disease (1).
A further 2 diseases each share a sentence with FAT2 in 1 paper.